RAG1 (recombination activating 1)
Diseases named in the same sentence as RAG1 in open-access papers (continued):
Sharing a sentence is not in itself a finding about the gene and the disease.
gastric cancer (3 papers, 2019 to 2021). A primary or metastatic malignant neoplasm involving the stomach. "These clinical data support the conclusions that NFATc3 in gastric cancer is over-expressed and that NFATc3 upregulation and RAG1 downregulation are significantly associated with poor prognosis." (PMID 31822296, 2019). "We further showed that NFATc3 upregulation and RAG1 downregulation significantly associated with poor prognosis in patients with gastric cancer." (PMID 31822296, 2019). "High expression of RAG1 was associated with high proliferation markers in adult ALL and poor prognosis in gastric cancer, which revealed the role of RAG1 in cancer progression." (PMID 33329712, 2020). "We show that arsenic sulfide as well as knockdown of NFATc3 resulted in increased double-strand DNA damage in gastric cancer cells by increasing the expression of RAG1, an endonuclease essential for immunoglobulin V(D) J recombination." (PMID 31822296, 2019). "Mechanistically, arsenic sulfide treatment of gastric cancer cells as well as knockdown of NFATc3 induce double strand DNA break and RAG1 expression." (PMID 31822296, 2019). "Our in vivo experiments further confirmed that arsenic sulfide exerted cytotoxic activity against gastric cancer cells through inhibiting NFATc3 to activate RAG1 pathway." (PMID 31822296, 2019). "The expression of recombination activating gene 1 (RAG1) in gastric cancer cell lines was determined by RNA-sequencing analyses and Real-Time qPCR." (PMID 31822296, 2019). "NFATc3 silencing abolished the transcriptional suppression of RAG1 leading to increased DNA DSBs in gastric cancer cells." (PMID 31822296, 2019). "The results showed that NFATc3 expression was significantly increased in the gastric cancer tissues while RAG1 expression was significantly decreased in the gastric cancer tissues." (PMID 31822296, 2019). "Low RAG1 gene expression is correlated with poor survival of gastric cancer patients." (PMID 33892676, 2021). "Interestingly, low RAG1 expression correlated with poor survival of gastric cancer patients (p = 0.029, HR = 0.69–0.98)." (PMID 31822296, 2019). "Our data suggest that low RAG1 expression correlates with poor survival of gastric cancer patients." (PMID 31822296, 2019). "We then further verified NFATc3 and RAG1 dysregulation in six pairs of gastric cancer tissues and matched adjacent nonmalignant tissues by qRT-PCR." (PMID 31822296, 2019).
Glucose intolerance (3 papers, 2019 to 2025). Glucose intolerance (GI) can be defined as dysglycemia that comprises both prediabetes and diabetes. "In the same study depletion of ILC2 in Rag1 KO mice increased weight gain and glucose intolerance, whereas adoptive transfer of ILC2 or NKT cells induced transient weight loss and stabilized glucose homeostasis in obese mice." (PMID 31191312, 2019). "Rag1−/− mice gained weight and fat mass under HFHSD feeding accompanied by glucose intolerance." (PMID 40328980, 2025).
Hepatic steatosis (3 papers, 2017 to 2022). Steatosis is a term used to denote lipid accumulation within hepatocytes. "Increased hepatic steatosis and skeletal muscle lipid accumulation measured in HFD-fed Rag1−/− mice in our study is, thus, a novel finding." (PMID 28352127, 2017). "NOD/SCID HFD-fed mice also developed symptoms of metabolic disturbance, including increased plasma insulin, insulin resistance, hepatic steatosis, and increased adipocyte size, however, these changes were more pronounced in HFD-fed Rag1−/− mice." (PMID 28352127, 2017).
Hepatitis (3 papers, 2012 to 2021). Inflammation of the liver. "RAG1.CBL tko mice also manifested exclusively liver inflammation, characterized by skin jaundice, massive liver infiltration of leukocytes and fibrosis, similar to that found in CBL-/-CBL-B-/- mice." (PMID 34630435, 2021). "Nine months after birth, tg1223/Rag1-/- and tg1223/ Ikkβ∆hep livers showed no signs of hepatitis, increased hepatocyte, or oval-cell proliferation." (PMID 23233866, 2012).
Hyperinsulinemia (3 papers, 2019 to 2024). An increased concentration of insulin in the blood. "The administration of B. uniformis normalized hyperinsulinemia in Rag1-/- mice fed HFHSD." (PMID 38845049, 2024). "Indeed, Rag1-/- mice fed a high-fat diet (42.2% kcal as fat) for 11 weeks gained more weight than C57BL/6 mice fed the same diet, and developed similar hyperinsulinemia and impaired glucose tolerance." (PMID 35533183, 2022).
Impaired glucose tolerance (3 papers, 2020 to 2022). An abnormal resistance to glucose, i.e., a reduction in the ability to maintain glucose levels in the blood stream within normal limits following oral or intravenous administration of glucose. "Immune-deficient Rag1-KO mice have been used in high-fat diet (HFD) experiments and shown to increase their body weight and to develop impaired glucose tolerance." (PMID 33670429, 2021).
IPEX syndrome (3 papers, 2021 to 2025). "While present in almost all categories, their burden and distribution vary, with certain defects acting as clear ‘hotspots’, such as IPEX syndrome, APECED, LRBA, RAG1, RAG2, CD3γ, Helios, ARPC1B, and CD55 deficiencies." (PMID 41394846, 2025).
lung adenocarcinoma (3 papers, 2016 to 2024). A carcinoma that arises from the lung and is characterized by the presence of malignant glandular epithelial cells. "In this study, adoptive (T/B-cell based) immunity-deficient RAG1−/− Sgo1−/+ double mutant mice developed lung adenocarcinomas more aggressively than did Sgo1−/+ or RAG1−/− mice, suggesting immune system involvement in CIN-mediated lung carcinogenesis." (PMID 27526110, 2016). "Interestingly, our analysis of COX-IS expression in TCGA lung adenocarcinoma cohort demonstrated increased activity of the COX2/PGE2 axis in RAG1 patients, which are associated with STK11/LKB1 co-occurring mutations." (PMID 38635884, 2024).
microcephaly (3 papers, 2009 to 2022). A congenital or acquired developmental disorder in which the circumference of the head is smaller than normal for the person's age and sex. "A patient with microcephaly, flat nasal bridge, short philtrum was suspected of a defect in DNA Ligase IV but was identified with a RAG1 defect." (PMID 30778343, 2019). "RAG1, RAG2, and DCLRE1C are the primary genes responsible for the T-B-NK+ SCID phenotype and in a recent report, mutations in LIG4 were also documented in patients with this phenotype who also have microcephaly and developmental delay." (PMID 19912631, 2009).
myositis (3 papers, 2015 to 2023). "Interestingly, CD4+ T cells from scurfy lymph nodes can also induce myositis and inflammation of the salivary glands (resembling Sjögren’s syndrome) upon transfer into susceptible (RAG-1-knockout) recipients." (PMID 25890083, 2015). "RAG1 KO mice developed markedly reduced muscle inflammation relative to WT mice, demonstrating a key requirement for T cells in driving HRS-induced myositis." (PMID 37809058, 2023).
periodontitis (3 papers, 2013 to 2022). An acute or chronic inflammatory process that affects the tissues that surround and support the teeth. "Most of the P. gingivalis rag-1 had higher scores for virulence in vivo than rag-4, and the rag-1 locus was associated with deep pockets in periodontitis patients." (PMID 33133418, 2020). "Porphyromonas.gingivalis carrying rag-1 has the strong virulence and could be associated with severe periodontitis." (PMID 23593379, 2013). "However, no significant rescue from the alveolar bone loss was detected in Pg-infected RAG1-deficient mice that lack both T and B cells, suggesting that RANKL from these lymphocytes is not critically important for osteoclast formation in the Pg-induced periodontitis model." (PMID 36333322, 2022). "In contrast, both Rag1−/−; Dmp1-Cre; Myd88fl/fl and Dmp1-Cre;Ranklfl/fl mice exhibited a significant rescue from alveolar bone osteolysis, thereby confirming that osteocytes are the primary source of RANKL in Pg-induced periodontitis." (PMID 36333322, 2022). "Importantly, our data from RAG1-deficient mice indicate that RANKL induction in osteocytes is independent of T and B cell activation in Pg periodontitis." (PMID 36333322, 2022).
prostate carcinoma (3 papers, 2017 to 2018). A carcinoma that arises from epithelial cells of the prostate gland. "In order to investigate the role of T and B cells in prostate cancer development, both adaptive immune cell types were genetically eliminated from Hi-Myc mice by crossing these mice with RAG1-/- mice." (PMID 29212195, 2017). "Although further studies are required, this study demonstrates that a Western 23% HFD in Rag1−/− mice increases the growth rate of prostate cancer xenografts and significantly decreases survival to ethical endpoint compared to low-fat chow-fed mice." (PMID 28352127, 2017). "Our study demonstrates that a Western 23% HFD increases fat mass, reduces insulin tolerance, increases LNCaP human prostate cancer xenograft growth, and decreases survival to ethical endpoints in male Rag1−/− mice." (PMID 28352127, 2017). "As UAG reduces prostate cancer proliferation in vitro and has potential beneficial metabolic effects in vivo, we examined the effect of UAG in our model of metabolic dysfunction: Rag1-/- mice fed a high-fat diet with subcutaneous prostate cancer cell line xenografts." (PMID 30458004, 2018). "Furthermore, a pilot study demonstrates that LNCaP human prostate cancer cell line xenografts grow more rapidly in Rag1−/− mice fed a Western HFD than tumours in control Rag1−/− mice fed a low-fat diet." (PMID 28352127, 2017). "In our diet-induced hyperinsulinaemic Rag1-/- mouse model, we investigated the effect of supraphysiological systemic UAG treatment (100μg/kg/day) on metabolic parameters and PC3 prostate cancer xenograft growth." (PMID 30458004, 2018). "Indeed, we reveal that engraftment of human prostate cancer cell line xenografts is possible in both HFD and chow-fed Rag1−/− mice, with tumours developing to a palpable size more rapidly in HFD-fed mice." (PMID 28352127, 2017).
Rectal prolapse (3 papers, 2018 to 2022). Protrusion of the rectal mucous membrane through the anus. "HCA2−/− Rag1−/− mice spontaneously develop rectal prolapse and exhibit immune cell infiltration of the intestinal lamina propria, which is not seen in Rag1−/− mice under the same conditions." (PMID 33708203, 2021).
rheumatoid arthritis (3 papers, 2008 to 2023). A chronic, systemic autoimmune disorder characterized by inflammation in the synovial membranes and articular surfaces. "Furthermore, expression of the recombination-activating genes RAG1 and RAG2 is evident in ectopic GC formed in rheumatoid arthritis and autoimmune thyroid diseases." (PMID 18716662, 2008).
Sepsis (3 papers, 2017 to 2025). Sepsis is defined as life-threatening organ dysfunction caused by a dysregulated host response to infection. "We further primed athymic nude mice and RAG1-deficient mice with CLP-induced sepsis." (PMID 33154574, 2021). "A similar increase of ILC2 was observed in the lung of sepsis-surviving Rag1−/− mice that lack mature T- and B-lymphocytes." (PMID 28374774, 2017). "Concordantly, sepsis-surviving Rag1−/− mice, which had increased the polarization of M2 macrophages, also showed elevated concentration of IL-10 in the lungs." (PMID 28374774, 2017). "Priming with the flo8 mutant provided no protection against lethal CLP-induced sepsis in RAG1-deficient or nude mice." (PMID 33154574, 2021).
vasculitis (3 papers, 2012 to 2024). "Also, in this study we show that T and B cells played a contributory role in the development of CAWS-induced vasculitis, as suggested by the decreased incidence of illness in Rag1−/− mice." (PMID 23074996, 2012). "But most importantly, Rag1−/− mice reconstituted with T and B cells from Ccr2−/− mice had significantly lower incidence of CAWS-induced vasculitis (16%) compared with WT mice." (PMID 23074996, 2012). "In our case series, only one patient was affected by congenital immunodeficiency (RAG1 deficiency) and no ANCA-associated vasculitis emerged." (PMID 37240876, 2023).
B cell deficiency (2 papers, 2017 to 2021). A broad classification of disorders where circulating numbers of B lymphocytes are decreased or ineffective. "In a mouse model of fracture, recombination activating gene 1 knockout mouse (Rag-1−/−, and T- and B-cell deficiency) showed delayed cartilage maturation and less mineralized tissue." (PMID 34150839, 2021). "Owing to targeted deletions of RAG1 (T-cell and B-cell deficiency) as well as of the type I and type II interferon genes, AGR mice readily reveal an attenuated virus' reversion to virulence." (PMID 28548102, 2017).
Bloom syndrome (2 papers, 2013 to 2017). Bloom syndrome (BSyn) is a rare chromosomal breakage syndrome characterized by a marked genetic instability associated with pre- and postnatal growth retardation, facial sun-sensitive telangiectatic erythema, increased susceptibility to infections, and predisposition to cancer. "Interestingly, T cell-related genes (D.3) were downregulated (Bloom syndrome, E2F transcription factor 1 and peroxiredoxin 2) in the RAG1−/− compared to the WT." (PMID 28596766, 2017).
celiac disease (2 papers, 2009 to 2021). An autoimmune genetic disorder with an unknown pattern of inheritance that primarily affects the digestive tract. "Third, children with coeliac disease have significantly decreased expression of both RAG1 in all three IEL-subtypes and of preTα mRNA in immature T cells, suggesting reduced extrathymic T cell maturation accompanied by decreased TCR editing and/or revision." (PMID 18299319, 2009). "By contrast, RAG1 and preTα mRNA levels were low in patients with coeliac disease compared to controls, both with active disease and with inactive, symptom-free disease on a gluten-free diet (p values <0.01 for mature and <0.05 for immature IELs)." (PMID 18299319, 2009). "The frequencies of IELs expressing the RAG1 protein were also compared between patients with coeliac disease and controls." (PMID 18299319, 2009). "Similarly, the frequencies of RAG1+ IELs were significantly lower in patients with coeliac disease compared to controls (p<0.001)." (PMID 18299319, 2009). "Therefore, we compared expression levels of RAG1 mRNA splice forms and preTα mRNA in T cell lineage subsets of IELs, using biopsies from children with coeliac disease, both in active and inactive disease, and from children with no food intolerance." (PMID 18299319, 2009). "Expression levels of the four splice-forms of recombination activating gene-1 (RAG1) mRNA and preT α-chain (preTα) mRNA were determined in IEL-subsets of children with coeliac disease and controls." (PMID 18299319, 2009). "In accordance with the low expression levels of RAG1 mRNA, we found very few RAG1+ IELs in the small intestine of children with coeliac disease irrespective of disease activity." (PMID 18299319, 2009).
Cerebral ischemia (2 papers, 2022 to 2024). Restriction of arterial blood supply to the brain associated with insufficient oxygenation to support the metabolic requirements of the tissue. "Finally, the Rag1−/− mouse model served as a proof-of-concept experiment to analyze the therapeutic effect of FTY720, a sphingosine-1-phosphate receptor modulator, in models of cerebral ischemia and to determine the contribution of lymphocytes to angiotensin II-induced microvascular dysfunction." (PMID 34105078, 2022).
Chronic lymphocytic leukemia (2 papers, 2022). "The following two pages deal with the expression of RAG1 and the miRNA regulating it in two datasets, Chronic lymphocytic leukemia, and T-cell Acute Lymphoblastic Leukemia, respectively." (PMID 35401578, 2022).
common variable immunodeficiency (2 papers, 2015). "For example, patients with Omenn syndrome or common variable immunodeficiency (CVID) carry hypomorphic mutations in RAG1/2, the enzymes that initiate recombination in B and T cells." (PMID 26544571, 2015).
diabetic kidney disease (2 papers, 2018 to 2019). Progressive kidney disorder caused by vascular damage to the glomerular capillaries, in patients with diabetes mellitus. "Accordingly, the T and B-cell deficient Rag1-deficient mice were protected from diabetic kidney disease as compared to Rag1-sufficient mice." (PMID 31191312, 2019).
eczema (2 papers, 2021). "However, comparable to our earlier observations and those reported from elsewhere, eczema is a consistent feature of HIGE syndrome and WAS and a predominant feature in patients with CID including DOCK8, RAG1, and MHC II deficiency." (PMID 34659256, 2021). "Even in the absence of adaptive immunity, Rag1 knockout mice fed a high-LCSFA milk diet develop eczema, accompanied by increased gut ILC3s." (PMID 34162906, 2021).
encephalitis (2 papers, 2019 to 2022). An acute inflammatory process affecting the brain parenchyma. "In WNV encephalitis, the disease is dependent on nitric oxide-producing monocytes/macrophages infiltrating the CNS parenchyma, while, similar to our results with the Rag1−/− mice, CD4+ and CD8+ T cells do not contribute significantly to pathology in the absence of peripheral infection." (PMID 31511023, 2019).
fungal infection (2 papers, 2020). "Although TRAF1 is well-known for its role in the regulation of B cell and T cell functions, we found that Rag1−/−Traf1−/− mice were still able to mount a better immune defense against fungal infection than Rag1−/− mice." (PMID 32093731, 2020).
glaucoma (2 papers, 2018 to 2023). Increased pressure in the eyeball due to obstruction of the outflow of aqueous humor. "We investigated if CD4+ T cells play a causal role in progressive neurodegeneration in glaucoma by adoptively transferring T cells from glaucomatous B6 mice into Rag1−/− mice." (PMID 30097565, 2018). "In particular, Rag1 plays a role in programmed cell death in the visual system, but it was detected solely in retinal ganglion cells in a model resembling features found in human glaucoma, but not in photoreceptors that are the target of our injury model." (PMID 37689689, 2023).